CYLC2 (cylicin 2)
Description:
Plays a role in the establishment of normal sperm morphology during spermatogenesis. It is required for acrosome attachment to the nuclear envelope, and proper manchette elongation and disassembly.
Tractability: PROTAC: ubiquitination databases record sites on it.
Gene: Protein-coding gene on chromosome 9 (102,995,311 to 103,018,488, forward strand). Ensembl gene ENSG00000155833.
Subcellular location: Cytoplasm, cytoskeleton, perinuclear theca, calyx; Cytoplasm, cytoskeleton, perinuclear theca
Subcellular location (Human Protein Atlas): Calyx; Perinuclear theca
Gene Ontology:
Molecular function: structural constituent of cytoskeleton
Biological process: spermatogenesis; cytoskeleton organization
Cellular component: nucleus; perinuclear theca; sperm glycocalyx; cytoskeletal calyx
Genetic constraint (gnomAD): Loss-of-function variants: 21 observed, 18.72 expected, observed/expected ratio (o/e) 1.12, 90% interval 0.79 to 1.61. The upper end of that interval is the gene's LOEUF score, 1.61, which puts it in group 6 of 6, group 1 being the genes least tolerant of losing a copy. Missense variants: 453 observed, 367.36 expected, observed/expected ratio (o/e) 1.23, 90% interval 1.14 to 1.33. Synonymous variants: 139 observed, 126.83 expected, observed/expected ratio (o/e) 1.1, 90% interval 0.95 to 1.26.
Homologues: Orthologues: chimpanzee CYLC2 (95% identical), macaque CYLC2 (87% identical), pig CYLC2 (63% identical), dog CYLC2 (59% identical), mouse Cylc2 (46% identical), rat Cylc2 (44% identical). Paralogues in human: CYLC1 (38% identical).
Diseases named in the same sentence as CYLC2 in open-access papers:
CYLC2 is named in the same sentence as 5 diseases in open-access papers, as found by Europe PMC text mining. Sharing a sentence is not in itself a finding about the gene and the disease. The quoted sentences say what the papers report.
infertile (2 papers, 2023 to 2024). "Overall, the identification and detailed characterization of further patients with variants in CYLC1 and CYLC2 is warranted to draw firm conclusions on the effect of variants in these genes on spermiogenesis and infertility." (PMID 38013430, 2023). "As loss of two Cylicin alleles causes fertility defects in mice, we next addressed whether infertile men also display variants in CYLC1/CYLC2." (PMID 38013430, 2023). "Furthermore, exome sequencing identified an infertile man with a hemizygous variant in CYLC1 and a heterozygous variant in CYLC2, displaying morphological abnormalities of the sperm including the absence of the acrosome." (PMID 38013430, 2023). "The CYLC2 missense variant is inherited by the father of M2270 and, thus, not sufficient to cause infertility." (PMID 38013430, 2023).
male infertility (2 papers, 2023 to 2024). The inability of the male to effect fertilization of an ovum after a specified period of unprotected intercourse. "This hypothesis is supported by our finding that Cylc1 deficiency causes subfertility in male mice, while the loss of both Cylc2 alleles results in male infertility." (PMID 38013430, 2023). "Knockout of Cylicin 1 leads to low fertility in male mice, and the knockout of any two copies of Cylicin 1 and Cylicin 2 can result in male infertility." (PMID 39765560, 2024).
dysentery (1 paper, 2012). Acute inflammation of the intestine associated with infectious diarrhea of various etiologies, generally acquired by eating contaminated food containing toxins, biological derived from bacteria or other microorganisms. "Two SNPs in the cylicin-2 gene (EHI_080100/XM_001914351) were associated with disease (asymptomatic/diarrhea p = 0.0162 or dysentery/amebic liver abscess p = 0.0003)." (PMID 22839995, 2012). "Non-Reference SNPs in the EHI_080100 cylicin-2 gene were significantly associated with the virulence phenotype (amebic liver abscess > asymptomatic > diarrhea or dysentery)." (PMID 22839995, 2012).
lung carcinoma (1 paper, 2018). "As a second case study, we examined an ESP associated with aggressive lung cancer, mutated in 22% of lung tumors and involving mutations to the genes CYLC2, STK11 and STK11P." (PMID 30297789, 2018).
CYLC2 also shares sentences with these, for which no sentence is quoted: obsessive-compulsive disorder (1 paper).